Y_RNA (Y RNA )
Gene: Miscellaneous RNA gene on chromosome 1 (246,426,006 to 246,426,119, reverse strand). Ensembl gene ENSG00000207326.
Homologues: Orthologues: chimpanzee Y_RNA (100% identical). Paralogues in human: Y_RNA (85% identical), RNY1 (84% identical), Y_RNA (84% identical), Y_RNA (83% identical), Y_RNA (82% identical), RNY1P10 (82% identical), RNY1P11 (82% identical), RNY1P8 (82% identical), Y_RNA (81% identical), Y_RNA (80% identical), Y_RNA (79% identical), Y_RNA (78% identical), and 94 more.